MUL1 (mitochondrial E3 ubiquitin protein ligase 1)
Description:
Exhibits weak E3 ubiquitin-protein ligase activity. E3 ubiquitin ligases accept ubiquitin from an E2 ubiquitin-conjugating enzyme in the form of a thioester and then directly transfer the ubiquitin to targeted substrates. Can ubiquitinate AKT1 preferentially at 'Lys-284' involving 'Lys-48'-linked polyubiquitination and seems to be involved in regulation of Akt signaling by targeting phosphorylated Akt to proteasomal degradation. Proposed to preferentially act as a SUMO E3 ligase at physiological concentrations. Plays a role in the control of mitochondrial morphology by promoting mitochondrial fragmentation, and influences mitochondrial localization. Likely to promote mitochondrial fission through negatively regulating the mitochondrial fusion proteins MFN1 and MFN2, acting in a pathway that is parallel to the PRKN/PINK1 regulatory pathway. May also be involved in the sumoylation of the membrane fission protein DNM1L. Inhibits cell growth. When overexpressed, activates JNK through MAP3K7/TAK1 and induces caspase-dependent apoptosis. Involved in the modulation of innate immune defense against viruses by inhibiting RIGI-dependent antiviral response. Can mediate RIGI sumoylation and disrupt its polyubiquitination.
Synonyms: C1orf166; GIDE; MAPL; MULAN; RNF218; FLJ12875
Tractability: Antibody: UniProt predicts a signal peptide or a membrane-spanning region. PROTAC: UniProt records ubiquitination sites on it; ubiquitination databases record sites on it; its protein half-life has been measured.
Gene: Protein-coding gene on chromosome 1 (20,499,445 to 20,508,151, reverse strand). Ensembl gene ENSG00000090432.
Subcellular location: Mitochondrion outer membrane; Peroxisome
Subcellular location (Human Protein Atlas): Cytosol; Mitochondria; Nucleoplasm
Pathways (Reactome):
Metabolism of proteins: Neddylation; Ub-specific processing proteases
Cellular responses to stimuli: KEAP1-NFE2L2 pathway
Gene Ontology:
Molecular function: identical protein binding; protein binding; SUMO transferase activity; ubiquitin protein ligase activity; ubiquitin protein ligase binding; ubiquitin-protein transferase activity
Biological process: cellular response to exogenous dsRNA; mitochondrial fission; mitochondrion localization; negative regulation of chemokine (C-C motif) ligand 5 production; negative regulation of defense response to virus by host; negative regulation of innate immune response; negative regulation of mitochondrial fusion; negative regulation of phosphatidylinositol 3-kinase/protein kinase B signal transduction; negative regulation of type I interferon-mediated signaling pathway; positive regulation of canonical NF-kappaB signal transduction; positive regulation of cGAS/STING signaling pathway; positive regulation of mitochondrial fission; positive regulation of protein sumoylation; protein destabilization; protein K63-linked ubiquitination; protein polyubiquitination; protein stabilization; protein ubiquitination; regulation of mitochondrial outer membrane permeabilization involved in apoptotic signaling pathway; regulation of mitochondrion organization; positive regulation of dendrite extension; positive regulation of developmental process; positive regulation of type 2 mitophagy; protein sumoylation; regulation of anatomical structure morphogenesis; and 2 more
Cellular component: axon; membrane; mitochondrial outer membrane; mitochondrion; neuronal cell body; peroxisome; TOM complex
Genetic constraint (gnomAD): Loss-of-function variants: 25 observed, 29.2 expected, observed/expected ratio (o/e) 0.86, 90% interval 0.62 to 1.2. The upper end of that interval is the gene's LOEUF score, 1.2, which puts it in group 5 of 6, group 1 being the genes least tolerant of losing a copy. Missense variants: 379 observed, 423.45 expected, observed/expected ratio (o/e) 0.9, 90% interval 0.82 to 0.97. Synonymous variants: 180 observed, 176.66 expected, observed/expected ratio (o/e) 1.02, 90% interval 0.9 to 1.15.
Homologues: Orthologues: chimpanzee MUL1 (100% identical), macaque MUL1 (99% identical), guinea pig MUL1 (93% identical), rabbit MUL1 (93% identical), rat Mul1 (90% identical), mouse Mul1 (90% identical), dog MUL1 (88% identical), pig MUL1 (79% identical), zebrafish mul1 (62% identical), tropical clawed frog mul1 (57% identical), Drosophila melanogaster Mul1 (28% identical), Caenorhabditis elegans exc-14 (19% identical).
Diseases named in the same sentence as MUL1 in open-access papers:
MUL1 is named in the same sentence as 54 diseases in open-access papers, as found by Europe PMC text mining. Sharing a sentence is not in itself a finding about the gene and the disease. The quoted sentences say what the papers report.
head and neck cancer (7 papers, 2015 to 2024). A primary or metastatic malignant neoplasm affecting the head and neck. "We reported that MUL1 regulation was associated with head and neck cancer (HNC) development through reduction of AKT." (PMID 29299162, 2017). "The first study in head and neck cancer (human SCC15 and mouse SCC7) cells found that CP increased apoptosis, concurrent with reduced Akt phosphorylation and expression through MUL1-encoded E3 ligase-mediated ubiquitination." (PMID 38785562, 2024). "In head and neck cancer, MUL1 induces the ubiquitination of HSPA5 at lysine 446, which triggers cell apoptosis." (PMID 36982218, 2023). "Previously our studies showed that mitochondrial E3 ubiquitin protein ligase 1 (MUL1, also known as MULAN/GIDE/MAPL) is suppressed in head and neck cancer (HNC) and acts as negative regulator against AKT." (PMID 29299162, 2017). "Furthermore, tumour growth in a mouse model of head and neck cancer was slowed and eventually stopped with CP treatment, with increased MUL1 expression and decreased Akt phosphorylation confirmed immunohistochemically." (PMID 38785562, 2024). "NBP-induced ROS has been shown to mediate AKT degradation through the activation of the AKT ubiquitin-proteasome system, mitochondrial E3 ubiquitin protein ligase 1 (MUL1) in head and neck cancer cell lines, and therefore to suppress cancer growth in vitro and in vivo." (PMID 31049127, 2019). "It has been reported that ROS upregulated mitochondrial E3 ubiquitin protein ligase 1, induced AKT ubiquitination, and promoted proteasome degradation in head and neck cancer." (PMID 35721212, 2022).
Parkinson disease (7 papers, 2014 to 2025). A progressive degenerative disorder of the central nervous system characterized by loss of dopamine producing neurons in the substantia nigra and the presence of Lewy bodies in the substantia nigra and locus coeruleus. "Together, these results indicate that MUL1 compensates for Parkinson’s phenotypes, caused by the loss of PINK1/Parkin or VSP35, by decreasing MFN2." (PMID 31156446, 2019). "In conclusion, in the present study, we found that mul1 and park mutations, which are involved in the development of Parkinson’s disease, disturb several processes in an organism, including circadian rhythms in behaviour and the molecular mechanism of the clock." (PMID 31138137, 2019). "Mutants which carry mutations in genes encoding mitochondrial ligases MUL1 and PARKIN are convenient Drosophila models of Parkinson’s disease (PD)." (PMID 31138137, 2019). "Moreover, a role of MUL1 in the degradation of MFN2 was suggested in the context of dopaminergic (DA) neuronal loss, closely related to Parkinson’s and Alzheimer’s diseases." (PMID 31156446, 2019). "MUL1 and PARKIN proteins are responsible for mitophagy and seem to be involved in the development of Parkinson’s disease." (PMID 31138137, 2019). "In addition to molecular symptoms such as those observerd in mul1 and park mutants, Parkinson’s disease are also characterized by other motor and non-motor symptoms." (PMID 31138137, 2019).
cardiac hypertrophy (3 papers, 2021 to 2025). "Furthermore, only male mice developed cardiac hypertrophy, as assessed by the heart weight-to-tibia length ratio, supporting the protective role of E2 in the hypertrophic response associated with increased MUL1 expression." (PMID 39971924, 2025). "MUL1 is upregulated in several models of cardiac hypertrophy, promoting mitochondrial fragmentation and dysfunction." (PMID 39971924, 2025). "Our research sheds light on the role of MUL1 in regulating cardiac hypertrophy and its potential implications for heart failure development." (PMID 39971924, 2025). "Moreover, our results from the transgenic animal model overexpressing MUL1 show that only males exhibit markers of cardiac hypertrophy, with females likely being protected by E2." (PMID 39971924, 2025). "Since MUL1 is an important protein in the induction of cardiac hypertrophy, we aimed to assess whether E2 prevented its induction." (PMID 39971924, 2025).
ischemic stroke (3 papers, 2022 to 2025). A stroke disorder caused by obstruction of blood flow to the brain, due to thrombotic (local blood clot formation) or embolic (due to a blood clot or other material traveling from another site) event. "Both MFN2 and DRP1 have been reported as MUL1 targets, whose levels also concomitantly change in other pathological conditions, such as ischemic stroke." (PMID 37051468, 2023). "The downregulation of Mfn2 by Mul1 increased the fragmented mitochondria concomitant with the mitochondrial dysfunction and cell deaths after the experimental ischemic stroke." (PMID 36531208, 2022). "The downregulation of Mfn2 by Mul1 exacerbated mitochondrial dysfunction and cell death after ischemic stroke." (PMID 36531208, 2022). "The downregulation of Mfn2 by Mul1 increased the fragmented mitochondria concomitant with mitochondrial dysfunction and cell death in ischemic stroke." (PMID 36531208, 2022).
thyroid cancer (3 papers, 2017 to 2023). "Regarding that CDDP induced K48-linked ubiquitylation of AKT, we checked the MUL1 expression level in response to CDDP treatment in thyroid cancer cells." (PMID 29299162, 2017). "MUL1 was considered to be a tumor suppressor protein in thyroid cancer, therefore further investigation was conducted in the interest of identifying regulators of MUL1." (PMID 29299162, 2017). "Moreover, as shown in thyroid cancer cells, treatment with cisplatin was able to reduce Akt levels in a MUL1-dependent manner, and this mechanism is ultimately mediated by the action of FOXO3." (PMID 38139010, 2023). "Here we report that cisplatin (CDDP) induces thyroid cancer cell death through MUL1-AKT axis." (PMID 29299162, 2017). "Following these reports, we hypothesized that MUL1 suppression may also contribute to development of thyroid cancer, thus we checked the relationship between CDDP-induced ubiquitylation of AKT and MUL1 induction." (PMID 29299162, 2017). "From the results of the present study, MUL1 was suppressed endogenously in thyroid cancer cells, thus MUL1 may act as a thyroid cancer suppressor protein through regulation of AKT activity." (PMID 29299162, 2017). "To determine whether MUL1 is associated with thyroid cancer cell survival, we transfected EGFP-MUL1 in TPC1 cells and measured cell viability." (PMID 29299162, 2017). "Thus, FOXO3 could be a good therapeutic target for thyroid cancer therapy through induction of the MUL1-AKT axis." (PMID 29299162, 2017). "The CDDP treatment, thus, results in MUL1-mediated ubiquitination and proteolysis of AKT, constituting a good therapeutic loop for HNC and thyroid cancer patients." (PMID 36672167, 2023). "FOXO3 was determined as a putative regulator of MUL1, therefore FOXO3 and MUL1 were suppressed in thyroid cancer cells." (PMID 29299162, 2017). "MUL1 overexpression reduced both p-AKT and total AKT levels in BHP10-1 and TPC1 thyroid cancer cells." (PMID 29299162, 2017). "On the other hand, when two mito E3s act as tumor suppressors (such as in thyroid cancer for RNF185 and MUL1), induction of both enzymes could achieve a synergistic effect on cancer inhibition." (PMID 38139010, 2023). "MUL1 is downregulated in head and neck cancer (HNC), and also in thyroid cancer." (PMID 36672167, 2023). "Although more detailed experiments are necessary to elucidate the underlying expression profiling between FOXO3 and MUL1 in tissues of thyroid cancer patients, we could speculate that while p-AKT is increased, FOXO3 and MUL1 is decreased." (PMID 29299162, 2017).
viral infection (2 papers, 2025). "Among them, MUL1 was an immune-related protein gene that participates in regulating the body’s innate immune response to against viral infections by inhibiting the RIG-I-dependent antiviral response." (PMID 41465762, 2025).
behavioral disorders (1 paper, 2019). "It has been reported that oxidative stress is associated with behavioral disorders in mice and we demonstrated that the mul1 or park overexpression in neurons can restore the normal level of apoptosis and increase autophagy and endogenous antioxidant enzyme levels." (PMID 30837828, 2019).
breast carcinoma (1 paper, 2023). "Based on these reports, a therapy involving MUL1 inactivation, either by gene therapy or by developing a specific pharmacological inhibitor, could be useful to achieve cancer regression in breast cancer, lung cancer and glioma." (PMID 38139010, 2023). "Moreover, from a therapeutic standpoint, the inhibition of a single mitoE3 could cause an increase in another one, in the context where two of them both act as oncogenes (for example, in breast cancer for MUL1 and MARCH5)." (PMID 38139010, 2023).
Cerebral ischemia (1 paper, 2024). Restriction of arterial blood supply to the brain associated with insufficient oxygenation to support the metabolic requirements of the tissue. "Furthermore, GCK treatment could decrease the binding affinity of Mul1 and Mfn2, inhibit Mul1/Mfn2-mediated ubiquitination and degradation, and increase the protein level of Mfn2 in cerebral ischemia-reperfusion injury." (PMID 38650626, 2024).
cervical intraepithelial neoplasia (1 paper, 2015). "In addition, another recent study demonstrated that MUL1 DNA methylation is a potential biomarker in Iranian females with cervical intraepithelial neoplasia and dysplasia." (PMID 26450902, 2015).
cognitive decline (1 paper, 2021). "However, little is known about the association between MUL1 and cognitive decline in PD or other neurodegenerative diseases that cause dementia." (PMID 34946922, 2021). "When MUL1 is downregulated, cortical neurons, as well as dopaminergic neurons, might become more susceptible to damage due to mitochondrial dysfunction, leading to the progression of cortical neuronal loss, synaptic dysfunction, and cognitive decline." (PMID 34946922, 2021). "Considering that the MUL1 pathway regulates mitochondrial damage in both dopaminergic and cortical neurons, defects in the MUL1 pathway might affect the cognitive decline in PD." (PMID 34946922, 2021).
dementia (1 paper, 2021). Loss of intellectual abilities interfering with an individual's social and occupational functions. "Further studies are needed to elucidate the exact pathogenic mechanisms underlying the involvement of MUL1 in the development of dementia in PD." (PMID 34946922, 2021). "This microarray genomic study identified new loci of MUL1 associated with dementia in PD, suggesting an essential role of mitochondrial dysfunction in the development of dementia in patients with PD." (PMID 34946922, 2021). "In the analysis performed for patients with PD only, MUL1 SNP rs3738128 (odds ratio = 2.52, 95% confidence interval = 1.68–3.79, p = 8.75 × 10−6) was found to be most significantly associated with dementia in PD." (PMID 34946922, 2021). "This microarray genomic study identified the new loci of MUL1 associated with dementia in PD, suggesting an essential role of mitochondrial dysfunction in the development of this nonmotor symptom of PD." (PMID 34946922, 2021). "MUL1 SNP rs3738128 (OR = 2.52, 95% CI = 1.68–3.79, p = 8.75 × 106) was most significantly associated with dementia in PD." (PMID 34946922, 2021). "The significant association of MUL1 with dementia in PD suggests the biological plausibility of the involvement of mitochondrial dysfunction in the development of dementia in PD." (PMID 34946922, 2021). "The MUL1 SNP rs3738128 showed the most significant association with dementia in PD." (PMID 34946922, 2021). "There were few studies investigating the role of MUL1 in the development of dementia in PD, and one case-control study conducted in China showed that MUL1 SNP rs529974 was correlated with the development of PD." (PMID 34946922, 2021).
glioma (1 paper, 2023). A benign or malignant brain and spinal cord tumor that arises from glial cells (astrocytes, oligodendrocytes, ependymal cells). "MUL1 has also been identified as a marker of poor prognosis for gliomas: although the molecular mechanisms are still to be identified, high expression of MUL1 in glioma patients is associated with lesser survivability." (PMID 38139010, 2023).
Insulin resistance (1 paper, 2024). Increased resistance towards insulin, that is, diminished effectiveness of insulin in reducing blood glucose levels. "Glucose tolerance and insulin resistance were also monitored in both Mul1(−/−) and Mul1(+/+) animals on HFD." (PMID 38725872, 2024). "Consequently, our data advocate the potential of MUL1 as a therapeutic target for drug development in the treatment of obesity, insulin resistance, NAFLD, and cardiometabolic diseases." (PMID 38725872, 2024).
leukemia (1 paper, 2020). A malignant (clonal) hematologic disorder, involving hematopoietic stem cells and characterized by the presence of primitive or atypical myeloid or lymphoid cells in the bone marrow and the blood. "If NTS could regulate MUL1 or RNF126 activity at the same time, NTS will be a strong therapeutic tool for leukemia therapy compared to other drugs (e.g., Imatinib) through AKT or mTOR ubiquitination." (PMID 32131492, 2020).
lung carcinoma (1 paper, 2023). "These preliminary studies, which still need in vivo confirmation, suggest an oncogenic role for MUL1 in breast and lung cancer." (PMID 38139010, 2023). "Especially in lung cancer, MUL1 could have an oncogenic role: its levels can be induced by cigarette smoke, leading to alteration in lung vascular epithelial cells." (PMID 38139010, 2023).
metabolic syndrome (1 paper, 2024). A cluster of metabolic risk factors for CARDIOVASCULAR DISEASES and TYPE 2 DIABETES MELLITUS. "Genetic deletion of Mul1 in mice impedes mitophagy and presents a metabolic phenotype that is resistant to high-fat diet (HFD)-induced obesity and metabolic syndrome." (PMID 38725872, 2024).